IL18 (interleukin 18)
Diseases named in the same sentence as IL18 in open-access papers (continued):
Sharing a sentence is not in itself a finding about the gene and the disease.
tumor (continued). "These genes included those related to P/DAMP signaling (e.g., Il6, Tlr1, Tlr4, Il1b, Il18), necroptotic tumor cell death (e.g., Casp1, Casp8, Il1b), and activation of the adaptive immune system (e.g., Cd80, Cd8a, Ccr5, Cxcl10)." (PMID 37213298, 2023). "On the same line, Membrane Spanning 4-Domains A4A (MS4A4A)+ macrophages have been described for their anti-tumor function, in view of their ability to release pro-inflammatory cytokines, including IL-15 and IL-18, upon engagement of Dectin-1 by tumor cells." (PMID 37298470, 2023). "It is interesting to note that these studies have also shown that IL-18 can synergize with αPD-1 immunotherapy or chemotherapy for stronger antitumor immunity and tumor growth inhibition." (PMID 37298187, 2023). "When the NLRP3 inflammasome is activated, mature IL-1 β and IL-18 are produced, resulting in tumor cell infiltration, metastasis, and angiogenesis." (PMID 37715239, 2023). "Energetic efforts have been placed to improve CAR-T activity in solid tumors by building novel cellular constructs engineered to express immunostimulatory checkpoints including CD28 and OX-40, specific tumor antigens or effector cytokines such as IL-12, IL-18." (PMID 37896948, 2023). "We therefore evaluated the potential of combining IL-18 therapy with A2AR blockade through engineering tumor cells to secrete IL-18." (PMID 37914685, 2023). "GSDMD (p = 0.012) and IL-18 (p < 0.001) were highly expressed in tumor tissues, whereas NLRP3 (p < 0.001) and CASP1 (p = 0.001) expression was low in tumor tissues." (PMID 37864196, 2023). "Recent research has demonstrated that tumor-infiltrating lymphocytes (TILs) upregulate the secretion of IL-18 through inflammasomes." (PMID 37561524, 2023). "In contrast, although Nigericin causes initial tumor cell death in tumor cell lines with strong NLRP3 activation and IL-1β and IL-18 production, cells recover and tumors remain active." (PMID 37715239, 2023). "The combination of NF-κB inhibition and IL-18 administration to mice significantly reduced tumor growth, taking advantage of both properties of the cytokine." (PMID 37298187, 2023). "IL-18 is expressed in epithelial and myeloid cells with a dual role in tumor progression and suppression." (PMID 37033931, 2023). "Cytokine-induced memory-like (CIML) NK cells, which differentiate after being activated with interleukin-12 (IL-12), IL-15, and IL-18, have been observed to possess enhanced anti-tumor responses." (PMID 36932395, 2023). "ELISA measurements in B7H4 staining positive tumours: IL-9, IL-18, IP-10(CXCL10), MIG (CXCL9) and SDF-1a (CXCL12)." (PMID 36980202, 2023). "For example, some studies have shown that blocking IL-1β or IL-18 can inhibit tumor growth or metastasis, while others have proven that inhibiting NLRP3 inflammasome can enhance tumor growth or metastasis." (PMID 37715239, 2023). "Tumor development and metastasis were suppressed in mouse models when both IL-18 inhibitor and PD-1/PD-L1 inhibitor were coupled." (PMID 37033931, 2023). "Here, we found that macrophage-secreted IL-18 upregulated LAT2 in tumor cells, which enhanced the uptake of Gln and Leu to upregulate CD47 for inhibition of macrophage phagocytosis." (PMID 36274066, 2022). "These researchers also indicated that IL-18 demonstrates beneficial characteristics in improving ACT responses based on the finding that IL-18 enhanced the tumor-targeting capacity of OVA-specific T lymphocytes." (PMID 35634281, 2022). "vHsv-IL12 and vHsv-IL-18 demonstrated a stronger anti-tumour effect than any other combinations of two vectors." (PMID 36140243, 2022). "Eotaxin, IL-6, and IL-18 levels were lower in the Chemo+Fish Oil group when compared with the Chemotherapy (eotaxin/IL-6) or Tumor (IL-18) groups, respectively (p < 0.05)." (PMID 36428795, 2022). "Intercompartmental IL9 and IL18 gradients were assessed in matched samples of tumor epithelium, stroma, and serum of patients." (PMID 36131941, 2022).
tumor (continued). "A study showed that the inhibition of IL-18 through TLR2 alleviated mouse HCC progression, whereas deletion of the IL-18 receptor enhanced tumor growth once the IL-18 had tumor-suppressive effects by promoting tumor-infiltration T cells." (PMID 36289606, 2022). "VEGF promotes angiogenesis and matrix metalloproteinases exacerbate inflammation and exudation, while interleukin-18 damages the function of NK cells and T cells, thereby impairing the host's immune response to tumor antigens." (PMID 36684128, 2022). "IL-18 binding protein (a high-affinity IL-18 decoy receptor) limited the anti-tumor activity of IL-18 in mice." (PMID 35739593, 2022). "The release of pyroptosis-related molecules IL-1β and IL-18 can induce the infiltration and activation of tumor immune cells, which is helpful to the anti-tumor immune response." (PMID 36186792, 2022). "Our research showed that DC/IL-18 + IL-12/TAg infiltrated the tumor tissue the fastest and the most efficiently compared to other vaccine cells, while DC/TAg migrated the most quickly and effectively to the lymph nodes." (PMID 35372586, 2022). "The combination of recombinant IL-18 and immune checkpoint inhibitors led to synergistic inhibition of tumor growth in animal models of peritoneal dissemination of colon cancer." (PMID 35739593, 2022). "A possible explanation for this observation is the tumor-induced recruitment of circulatory IL18 and its accumulation in the pancreatic stroma which contributes to tumor progression and poor patient outcomes." (PMID 36131941, 2022). "For example, it has been demonstrated that tumor-derived interleukin (IL)-18 increases the immunosuppressive CD56dimCD16dim/- NK cell fraction in patients with triple-negative breast cancer (TNBC) and induces the expression of PD-1 in these cells." (PMID 35634343, 2022). "Previous research has already established the role of IL-18 in mediating the Th1/tumor-infiltrating lymphocyte response." (PMID 36294509, 2022). "AIM2 was also required for the production of IL-1β and IL-18, which promoted Treg accumulation and tumor growth in vivo." (PMID 35739593, 2022). "It should be emphasized that the DC/IL-18 + IL-12/TAg vaccine cells in the tumor tissue were estimated at 0.07%." (PMID 35372586, 2022). "On the other, IL-18 increases the numbers of tumor-infiltrating lymphocytes (TIL), as shown in subcutaneous model of melanoma." (PMID 35517498, 2022). "The use of the developed DC/IL-18 + IL-12/TAg vaccine cells in immunotherapy allowed for a statistically significant inhibition of MC38 cancer tumor growth." (PMID 35372586, 2022). "Multiparameter flow cytometry analysis of myeloid and lymphoid cells in tumors confirmed a high percentage of CD4+ and CD8+ T cells in the tumor tissue obtained from mice treated with DC/IL-18 + IL-12/TAg, 7 days after the administration of vaccines." (PMID 35372586, 2022). "Similar things happened in tumor cells, in which an NLRandP3-mediated release of IL-18 would downregulate CD70 on tumor cells and generate immune escape." (PMID 35978433, 2022). "IL-4, IL-6 and IL-10 are abundantly expressed in TME and play more pro-tumor role, while IL-2, IL-12, IL-15 and IL-18, which are immunomodulatory or pro-inflammatory factors, are restricted in the TME and play more anti-tumor role." (PMID 36698392, 2022). "Complicating the development of IL-18-based cancer immunotherapy are preclinical studies showing the IL-18 can promote tumor invasiveness and progression in some experiments." (PMID 35529882, 2022). "Tumor tissue obtained from mice treated with DC/IL-18 + IL-12/TAg revealed a significantly lower percentage of CD11b+ cells, and therein thus, the percentage of DC and TAM was observed." (PMID 35372586, 2022). "We subsequently analyzed the influence of the anatomical tumor localization on concentrations of CgA, the NETest, as well as IL-1β, IL-6, IL-8, IL-10, IL-18, and TNF." (PMID 36294509, 2022).
tumor (continued). "Conversely, supplementation with IL-18 or implantation of wild-type myeloid cells reduced tumor burden." (PMID 35733919, 2022). "Patients with low stromal IL18 expression (favorable prognosis) have their tumor-to-stroma gradient directed away from the stroma towards the tumor epithelium." (PMID 36131941, 2022). "An additional qPCR analysis of the tumour cells showed significant increases in Il2, Ifng, Il1b, and Il18, and decreases in Il4, Il5, and Tgfb1, indicative of Th1‐dominant immune response." (PMID 35430766, 2022). "Immunohistochemistry images derived from the HPA database showed that GSK3B and IL18 expression at protein level in tumour tissues was elevated in contrast with that in normal tissues, in line with findings of RNA expression levels." (PMID 36743929, 2022). "It has been shown that IL-18 exhibits a variety of biological activities with implications in tumour initiation and development." (PMID 35012533, 2022). "In another study, antigen-inducible IL-18 expression in engineered T cells led to a safe and effective anti-tumour response against a melanoma mouse model with the development of a favourable profile of T cell co-stimulatory and inhibitory receptors." (PMID 35205725, 2022). "Upon IL-2, IL-12, and IL-18 stimulation, Vδ2 T cells also induced cell cycle arrest in various tumor cells like bladder carcinoma (T24), breast cancer (MCF7) and melanoma (WM115)." (PMID 36429001, 2022). "It has been shown that cytotoxic drugs like doxorubicin, paclitaxel, topotecan, carboplatin and gemcitabine selectively co-operate with IL-18 to improve anti-tumor effectiveness." (PMID 36032110, 2022). "Cytokine levels significantly correlated with tumor grade (IL-6; p = 0.0070), prevalence of distant metastasis (IL-18; p = 0.0313), and disease progression over time (IL-10; p = 0.0033) but not tumor location." (PMID 36294509, 2022). "Severe necrosis and infiltration of NK cells, as well as CD4+ and CD8+ T cells, were observed in RdB/IL-12/IL-18-treated tumour tissues." (PMID 36140243, 2022). "IL18BP reduces the efficacy of endogenous IL-18 or recombinant IL-18 (rIL-18) administered to try to mediate improved anti-tumor activity." (PMID 35185932, 2022). "The IL-18 levels in tumor tissues from the ΔppGpp-injected group were also significantly higher than those in the VNP20009-injected group." (PMID 35847095, 2022). "The combination of IL-18 and IL-2 showed a synergistic anti-tumor effect in mice subcutaneously inoculated with a sarcoma." (PMID 35739593, 2022). "Depletion or Inhibition of LAT2 in tumor cells abrogated IL-18-induced suppression of macrophage phagocytosis and improved antitumor immunity." (PMID 36274066, 2022). "In our study, the effect of tumor antigen-activated DCs was enhanced by their additional genetic modifications for the production of IL-12 and IL-18." (PMID 35372586, 2022). "IL-18, in combination with IL-12, also increases proliferation, anti-tumor activity and IFN-γ production." (PMID 36429001, 2022). "Next, we performed a comparative analysis of the frequency and phenotype of the CD8+ T cells in a distant (spleen) and a close (draining lymph nodes, dLNs) SLO to the tumor site in the absence (control) or presence of systemic IL-12+IL-18 (12 + 18)." (PMID 36330506, 2022). "During pyroptosis, activated caspase-1 promotes the production of proinflammatory cytokines such as IL-18 an IL-1β7 to regulate the tumor immune microenvironment." (PMID 36384889, 2022). "While preclinical studies and clinical trials have almost only focused on the anti-tumor effects of anti-IL-1β, other research has examined improving the levels of IL-18 in the treatment of tumors." (PMID 35739593, 2022). "On the other hand, other studies demonstrate that IL-18 supports an anti-tumor response of Tc1 cells by positive regulation of T-bet and suppression of Tc2 cells." (PMID 36172343, 2022).
tumor (continued). "DCs genetically modified for the production of IL-18 and/or IL-12 and stimulated with TAg, and control cells were identified in lymph nodes and tumor tissue on the 3rd, 5th, and 7th days." (PMID 35372586, 2022). "In our studies, the fold-induction of the IL-18 AUC correlated well with the antitumor efficacy in mouse syngeneic tumor models either as a monotherapy or in combination with an anti-mPD-1 mAb." (PMID 35795558, 2022). "We asked if in this “cold” tumor model, systemic IL-12+IL-18 treatment was able to increase the capacity of CD8+ T cells to infiltrate the tumors." (PMID 36330506, 2022). "An efficacious dose in monkeys was projected by targeting the fold-induction of the IL-18 AUC same as that observed in mice where a complete tumor regression was found in 80% of mice in efficacy evaluations." (PMID 35795558, 2022). "Analyses of the HOS-derived tumor tissues showed that doxorubicin increased macrophage activation with M1-polarity, IL-18 secretion, and CD47 expression." (PMID 36274066, 2022). "The outcome of our analysis suggests that IL‐18 probably has anti‐cancer property on YAP1 overexpressed tumor cells which can be further clarified by in vitro studies." (PMID 34196131, 2022). "The IL-18 cytokine creates a proinflammatory environment, recruits bystander effector cells to the tumor site and enhances cytolytic activity." (PMID 35401506, 2022). "The anti-tumor effects of IL-18 are partly ascribed to the production of IFN-γ in Th1 cells and NK cells." (PMID 35739593, 2022). "Once there, the DCs phagocytose the tumor cells and release pro-inflammatory mediators in the tumor, such as IL-1β, IL-18, IFN-γ, among others." (PMID 36015189, 2022). "Splenocytes obtained from DC/IL-18 + IL-12/TAg treated mice showed more efficient cytotoxic activity towards MC38 tumor cells compared to spleen cells from MC38 control mice." (PMID 35372586, 2022). "IL-10 can also induce tumor progression by inhibiting many cytokines such as IL-1a, IL-1b, IL-6, IL-8, IL-12, and IL-18." (PMID 35186043, 2022). "Activating caspase-1 can either lead to cell death or tumor growth by upregulating the secretion of pro-inflammatory molecules such as IL-1β, IL-18, and FGF2." (PMID 35883451, 2022). "Inflammasomes, potent inducers of IL-1β and IL-18 and pyroptosis, act as double-edged swords in cancers by producing tumor-promoting proinflammatory cytokines or facilitation of antitumor immune responses." (PMID 36386141, 2022). "Upon the recognition of tumor antigens, myeloid cells, especially dendritic cells (DCs) and macrophages produce inflammatory cytokines such as type-1 IFNs, IL-12, IL-15, IL-18, IL-21 involved in the natural killer (NK) cell tumor-killing response." (PMID 36341428, 2022). "On the one hand, IL-1β and IL-18 were correlated with tumor growth, invasion, angiogenesis and metastasis." (PMID 35281845, 2022). "In vivo, IL-18 is not only essential to host defense against severe infection but also crucial to tumor rejection by augmenting the cytotoxic activity of T and NK cells." (PMID 36354688, 2022). "IL18RAP, short for interleukin 18 receptor accessory protein, expresses the accessory β-subunit of the heteromeric receptor for IL18, a cytokine regulating the immunity by its pro-inflammatory effect and promoting tumor initiation and progression." (PMID 35092558, 2022). "Chronic inflammation induced by pro-inflammatory cytokines such as IL-1β, IL6, and IL-18, released via pyroptotic cell death, is considered to drive tumor progression and immune evasion." (PMID 35432318, 2022). "Pyroptosis is a lysis form of programmed death triggered by inflammasome and can rapidly release cellular contents such as pro-inflammatory molecules (IL-1β and IL-18) and antigens into the tumor microenvironment to activate the immune response of the body." (PMID 35847844, 2022). "A recent study has shown that IL-18 correlates with the local Th1/tumor-infiltrating lymphocyte response in colorectal as well as in breast cancer." (PMID 36294509, 2022).
tumor (continued). "Using our KPC bearing OT-I mouse model, we observed a significant increase in CD8+ T cell infiltrating the tumor islets after IL-12+IL-18 stimulation with a lower average speed when compared to those from control mice." (PMID 36330506, 2022). "We observed that DC/IL-18 + IL-12/TAg was characterized by the best migration capacity to tumor tissue." (PMID 35372586, 2022). "A recent in vitro study demonstrated that immune checkpoint therapy with IL-18 combined with anti-PD-L1 or anti-CTLA4 inhibited tumor progression." (PMID 36552744, 2022). "We have previously demonstrated the potent antitumor capacity of IL-12+IL-18 cDNA (at higher doses) or IL-12 cDNA systemic expression in B16 and other murine tumor models in vivo (3LL and EL4)." (PMID 36330506, 2022). "This conclusion came from that elevated expression of IL-18 by tumor cells were observed in the serum of PCa patients." (PMID 36237303, 2022). "They bind to specific antigens on the tumor cell surface; secrete the cytokines IL-12, IL-15, and IL-18; and then recognize and eliminate tumor cells." (PMID 35410257, 2022). "TCGA database analysis revealed that LOX and IFI44 mRNA expressions were higher in ESCA tumor tissues, while IL18 and SLURP1 mRNA expressions were higher in normal tissues." (PMID 36090891, 2022). "Focusing on IL18, we found that patients with low stromal IL18 levels (prognostic beneficial) show a significant tumor-to-stroma gradient away from the stroma (and towards the tumor epithelium)." (PMID 36131941, 2022). "Overall, the future of HCC treatment modulating IL-1β and IL-18 should take into account the different backgrounds and a deep understanding of tumor biology and its interplay with the microenvironment integrated in a personalized medicine approach." (PMID 36289606, 2022). "IL-18 was shown to promote the anti-tumour activity of the CAR T cells through a widespread change to the immune profile at the TME, with a decrease in suppressive cells, including Tregs, CD103+ DCs, and M2 macrophages." (PMID 35205725, 2022). "To assess the functional impact of IL18 in PDA, we blocked IL18 using IL18-binding protein (IL18BP) in a patient-derived model using tumor bioprints." (PMID 36131941, 2022). "IL-1β has been shown to have a strong tumor-promoting role while conversely, IL-18 has anti-tumorigenic effects." (PMID 36439171, 2022). "Authors also evidenced that C26 tumor growth in the liver can be strongly inhibited by the production of IL-18 by hepatocytes." (PMID 35159208, 2022). "One important characteristic of pyroptosis is the release of cellular contents such as pro-inflammatory cytokines interleukin-1β (IL-1β) and interleukin-18 (IL-18), which actively regulate the immune profile of the tumour microenvironment." (PMID 35517821, 2022). "Further studies are needed to determine the precise conditions under which IL-18 promotes or inhibits tumor growth versus regression." (PMID 35529882, 2022). "Candida produces nitrosamines that alter cell proliferation and secretes cytokines such as tumor necrosis factor-alpha (TNF-α) and interleukin (IL) 18 (IL-18) that modulate the immune response and promote tumor cell adhesion to epithelial cells." (PMID 35642013, 2022). "IL-18 can also promote the invasion and metastasis of GC cells by inhibiting the production of anti-tumor factors." (PMID 36185234, 2022). "NLRP3-dependent IL-18 production prevents neoplasia, with IL-18 participating in intestinal epithelial barrier repair via IFN-γ production and STAT1 signaling." (PMID 36466902, 2022). "The combination of IL-12, IL-15 and IL-18 induces a memory-like NK cell which is long-lived and has enhanced anti-tumour effects." (PMID 34888493, 2021). "These IL18-secreting CAR T cells were able to modulate the tumor microenvironment and enhance the endogenous antitumor immune response." (PMID 34809678, 2021). "The role of C. albicans in tumor adhesion and metastasis has been associated with TNF-α and IL-18 18-20." (PMID 33754037, 2021).